CAT (catalase)
Diseases named in the same sentence as CAT in open-access papers (continued):
Sharing a sentence is not in itself a finding about the gene and the disease.
ulcer (continued). "Superoxide dismutase (SOD), catalase (CAT), and glutathione peroxidase (GSH-px) levels were significantly declined (4.0-, 3.90-, and 2.21-fold, respectively) in the ethanol-induced ulcer control group compared to the normal group." (PMID 28587230, 2017). "SOD, GPx, CAT and GSH all contribute to maintain anti-oxidant status during oxidative stress condition such as ulcers." (PMID 19570992, 2011). "PEBH and MEBH treatment resulted in significant reduction in ulcer index and MDA contents along with increase in the CAT levels (P < 0.05)." (PMID 21279184, 2008). "AA caused a significant reduction in body weight and induced macroscopic and microscopic ulcers, along with a significant decline of endogenous antioxidants (superoxide dismutase (SOD), catalase, and GSH), with a concomitant increase in MDA level and MPO activity." (PMID 40943092, 2025). "Enhancing SOD, CAT, and GSH-Px activities or reducing MDA levels could protect the gastric mucosa, suggesting antioxidant therapy as a potential ulcer treatment strategy." (PMID 40606619, 2025). "Moreover, a marked rise in CAT activity has been reported in PIC (5 or 10 mg/kg) and omeprazole groups by 41.66%, 60.41%, and 47.91 %, respectively, when compared with the ulcer control group." (PMID 35330107, 2022). "The extract reduced the ulcer index by 93.4%, accelerated ulcer healing, improved the mucin content of gastric tissues, showed normal levels of malondialdehyde (MDA) and protein, and also increased levels of SOD and CAT levels." (PMID 35502487, 2022). "The result revealed that administration of ZJP could obviously improve the activities of antioxidant enzymes (SOD and CAT), restore the depleted GSH content, and decrease the MDA level, thereby protecting the gastric mucosa against ethanol-induced ulcers." (PMID 35938492, 2022). "Antioxidant and nitric oxide free radical scavenging activity has been shown by bergapten, which may be responsible for its effectiveness as anti-ulcer agent and further validated by LPO, catalase, GST, GSH and SOD assay." (PMID 36467058, 2022). "Ethanol-induced ulcer model is frequently used for characterizing new gastric protective agents, because ethanol predominantly affects the glandular portion of the stomach, increases lipid peroxidation, and decreases SOD activity, CAT activity, and GSH level." (PMID 35335941, 2022). "Gastric catalase acitivities demonstrated no statistically significant change among groups in both ulcer models." (PMID 35946894, 2022). "Tissue levels of GSH, GPx, and catalase were significantly reduced by 60%, 68%, and 32%, respectively in the positive ulcer group as compared to the negative control group." (PMID 31404064, 2019). "However, these extracts somewhat, but insignificantly, recovered the activities of antioxidant enzymes, such as CAT and SOD in the serum, that were decreased by ulcer induction by ethanol instillation." (PMID 30400615, 2018). "However, AMHAE (200 mg/kg) pretreated animals displayed a significant rise in SOD (3.90-fold), CAT (4.33-fold), and GSH-px (2.42-fold) levels compared to the ulcer control group." (PMID 28587230, 2017). "Recently we reported ulcer protective, plantain banana enhancing antioxidants, superoxide dismutase (SOD), catalase (CAT) and glutathione peroxidase (GSH) and decreasing the free radicals, lipid peroxidation (LPO) and nitric oxide (NO) levels in the gastric mucosal homogenates without any anti-H." (PMID 24192345, 2013). "Induced SOD, CAT and GPx activities explains the decrease in LPO from 8.34 ± 0.13 nmol/mg protein in the ulcer control to 3.13 ± 0.13 nmol/mg protein in CS-1000 which is in correlation with the maintenance of baseline (intact) enzyme activity levels of SOD, CAT and GPx (p> 0.05)." (PMID 23228052, 2012). "The parameters observed include ulcer index, mucin content, non-sulphhydryl(NP-SH), catalase(CAT), lipid peroxidase(LPO) and superoxide dismutase(SOD)." (PMID 21593982, 2008).
ulcer (continued). "On the other hand, DTN pretreatment resulted in significant increases in GSH, GST, and catalase levels, as well as a decrease in LPO TBARS, indicating its antioxidant capability and demonstrating that the molecule possesses gastro-protective effects against ethanol-model ulcers." (PMID 35906691, 2022). "Conversely, YEO lowered the serum and gastric levels of MDA and restored the antioxidant enzyme GSH, SOD, and CAT activities in both gastric tissues and serum, identifying YEO’s antioxidant potential and further complying with the gastroprotective potential against ethanol-induced ulcers." (PMID 36432009, 2022). "At a dose-dependency (500 and 1000 mg/kg), this extract significantly increased mucus, SOD and catalase levels and decreased the ulcer index and thiobarbituric acid (TBARS), with similar values shown by the standard drug ranitidine (20 mg/kg), compared to the ulcer control group." (PMID 34641500, 2021). "Moreover, KFX (5,10 mL/kg) increased the prostaglandin E2 (52%) and cyclooxygenase-1 (30%) levels, and improved malondialdehyde (54%), superoxide dismutase (58%), catalase (39%), and nitric oxide (11%) and TNF-α (9%), IL-6 (11%), MMP-9 (54%) and MMP-2 (53%) of ulcer tissue." (PMID 31696757, 2019). "Furthermore, upregulation of protein and mRNA catalase levels 14 days after HBO2 treatment, but not after 7 days, was also observed in the ulcer tissue of patients with diabetic foot, indicating a time-course for the effect of HBO2 to prevail." (PMID 27656047, 2016).
myocardial infarction (53 papers, 2011 to 2025). Gross necrosis of the myocardium, as a result of interruption of the blood supply to the area, as in coronary thrombosis. "Future studies should focus on the impact of d-Gal in subjects having a deficiency in erythrocytes catalase such as, for example, patients suffering of acute myocardial infarction." (PMID 32748857, 2020). "Our analysis showed that increased activity of CAT was associated with elevated activity of GPx, which overexpression in mice was previously shown to prevent left ventricular failure after myocardial infarction." (PMID 29867936, 2018). "In human studies, percutaneous transluminal coronary angioplasty did not change enzymatic antioxidant defense, while decreased enzymatic activities of erythrocytes' superoxide dismutase and catalase were caused by acute myocardial infarct." (PMID 28058087, 2016). "In a study on isoproterenol-induced myocardial infarction in rats, α-pinene treatment significantly decreased lipid peroxidation and improved CAT and SOD activities and GSH levels." (PMID 38318342, 2024). "Previously ARG supplements reduced MDA levels, and elevated GSH and catalase in renal and liver injury in rats with myocardial infarction." (PMID 37427328, 2023). "Protection of the heart function, enhancement in SOD and CAT levels, attenuation in myocardial infarct size, reduction in MDA level, and especially decreased cardiomyocytes apoptosis were reported after carvacrol treatment." (PMID 36348778, 2022). "In ISO‐induced myocardial infarction, the J‐point, heart rate, creatine kinase, lactate dehydrogenase, superoxide dismutase, catalase, malondialdehyde, glutathion, and reactive oxygen species decreased in mice after 18β‐GA treatment." (PMID 34925811, 2021). "Myocardial Infarction induced a significantly lower catalase (CAT) activity in the I group when compared to the sham group." (PMID 29057895, 2017). "Mice over-expressing human catalase under control of a myeloid-specific promoter were subjected to myocardial infarction and both acute and chronic healing were determined." (PMID 24853285, 2014). "Additionally, SQ increases serum glutathione (GSH), superoxide dismutase (SOD), and catalase (CAT) levels in rats with myocardial infarction models." (PMID 38292136, 2023). "In addition, SQ can increase serum glutathione (GSH), superoxide dismutase (SOD), and catalase (CAT) levels in myocardial infarction model rats." (PMID 36406080, 2022). "The breakage of microspheres by catalase might produce oxygen, which lasted for at least two weeks, in a similar manner to myocardial infarction (1% O2)." (PMID 35877508, 2022). "In addition, myocardial infarction is associated with an antioxidant deficit, which includes decreased superoxide dismutase (SOD), glutathione peroxidase (GPx), and catalase (CAT) activities, as well as increased lipid peroxidation." (PMID 32751587, 2020). "A recent study showed that administration of EA reduces heart rate, systolic and diastolic blood pressure in isoproterenol induced myocardial infarction rats, and also an increase in superoxide dismutase, glutathione peroxidase, and catalase was observed (Kannan and Quine, 2011 ▶)." (PMID 25949953, 2015). "This study found a marked reduction in the activities of antioxidant enzymes (CAT, SOD, GST, and GPx) in rats with myocardial infarction compared to controls." (PMID 40668529, 2025). "Oxidative stress markers such as; Malondialdehyde (MDA), Superoxide Dismutase (SOD), Catalase (CAT), Glutathione (GSH) confirmed the induction of myocardial infarction." (PMID 39551811, 2024). "An oxygen release system has been prepared for in situ oxygen release in myocardial infarction, which consisted of hydrogen peroxide (H2O2) released microspheres, catalase, and an injectable thermosensitive hydrogel." (PMID 35877508, 2022). "ISO‐induced oxidative stress was determined by measuring antioxidant enzymes (SOD, MDA, CAT, and GSH) in the myocardial infarction mice." (PMID 34925811, 2021).
myocardial infarction (continued). "During myocardial infarction, superoxides produced at the injury site regulate SOD and CAT, leading to activity decrease and superoxide buildup that harms the myocardium." (PMID 34527070, 2021). "Our data corroborate other reports which showed that treatment with vinpocetine and nimodipine alone or in combination increased the activities of GSH, CAT, and SOD in isoproterenol-induced myocardial infarction in rats." (PMID 32104536, 2020). "The authors observed a decrease of Nrf2 protein levels in the left ventricle (LV) of a rat model of CHF following myocardial infarction (MI), with a consequent decrease of Nrf2-dependent antioxidant enzymes (HO-1, SOD2, and CAT) as well." (PMID 32575472, 2020). "In basic researches, Myr treatment protected isoproterenol- (ISO-) induced myocardial infarction via increasing superoxide dismutase (SOD) and catalase (CAT)." (PMID 31885808, 2019). "Furthermore, after intervention with carvacrol, its cardioprotective effects have been observed through the reduction of myocardial infarct size, the increase of superoxide dismutase (SOD) and catalase (CAT) levels, and the reduction of cardiomyocyte apoptosis." (PMID 40292260, 2025). "In our study, isoproterenol succeeded in the induction of the myocardial infarction condition in rats, as shown by elevated cardiac marker enzymes, irregularities in the heart rate, blood pressure, and ECG parameters, and the exhaustion of the anti-oxidant enzymes (GSH, SOD, and CAT)." (PMID 31288394, 2019).
COVID-19 (52 papers, 2020 to 2026). A disease caused by infection with severe acute respiratory syndrome coronavirus 2. "However, when analyzed in combination with SOD2 rs4880 and CAT rs1001179, this SNP contributes to a significant three-locus interaction, increasing the risk of severe COVID-19 (OR ≈ 3.81, p ≈ 0.000055)." (PMID 41209585, 2025). "For example, the depletion of antioxidants like glutathione, superoxide dismutase, and catalase has been linked to severe COVID-19 outcomes and may contribute to the persistence of long COVID symptoms." (PMID 38804402, 2024). "The analysis of the possible role of abzymes with catalase activity in patients with COVID-19 can improve our understanding of the causes of the various complications of this disease and contribute to the search for therapeutic approaches to prevent its severe course." (PMID 37373231, 2023). "In the patients who recovered from COVID-19, there was a decrease in the level of IgG3, which may cause increased catalase activity of their antibodies." (PMID 37373231, 2023). "Among the genes included in these pathways, we found NQO1, CAT, RETSAT, NDUFS3, and HSD3B7, which were all already found associated with COVID-19 severity from our gene-based burden test analysis." (PMID 41500120, 2026). "The activity of CAT and all antioxidant enzymes is exhausted over time, especially in COVID-19 cases with additional complications, as has been confirmed by many authors." (PMID 40332548, 2025). "Our results revealed that the CAT activity was significantly increased (36%) in the COVID-19 patients in comparison to the healthy controls, following the pattern of the SOD enzyme." (PMID 40332548, 2025). "The current study also examined the levels of antioxidant markers like SOD and CAT and found them to be significantly decreased in severe COVID-19 patients." (PMID 41328243, 2025). "The total oxidant status (TOS) level and the activity of the extracellular enzymes SOD and CAT were elevated in COVID-19 patient plasma samples." (PMID 40867576, 2025). "Specifically, individuals with the SOD1 G, SOD2 T, and CAT C combination had higher odds of severe COVID-19 (p = 0.0045; OR = 2.84), suggesting a collective, rather than isolated, influence of these antioxidant genes." (PMID 41209585, 2025). "Studies assessing panels of OS biomarkers (e.g., thiobarbituric acid reactive substances (TBARS) as a proxy for MDA) alongside antioxidant defences (SOD, CAT, GR) revealed a pronounced imbalance in COVID-19 patients." (PMID 41209585, 2025). "Another study conducted in an Iranian hospital showed that TAC, SOD, CAT, and NO levels were significantly reduced in severe COVID-19 patients (n = 120) compared to healthy individuals (n = 60)." (PMID 41328243, 2025). "We reported significantly higher CAT mRNA levels in the placentae of the v-COVID-19 (p = 0.009, 2.5-fold increase) and u-COVID-19 (p = 0.04, 1.4-fold increase) subgroups compared to the v-CTRL subgroup." (PMID 39768279, 2024). "The blood plasma IgGs of patients who recovered from COVID-19 (group 1) had the highest catalase activity; the median value of the apparent kcat for this group was statistically 1.8 times higher than that for the IgGs of the healthy donors (group 4)." (PMID 37373231, 2023). "It was interesting to see how the change in catalase activity occurred in patients with COVID-19 and in patients immunized with Sputnik V compared to conditionally healthy donors." (PMID 37373231, 2023). "Overall, it cannot be ruled out that the immune system, in response to oxidative stress that occurs with COVID-19, can activate the production of antibodies with catalase activity." (PMID 37373231, 2023). "The catalase activity was comparable for the κ,κ-IgGs and λ,λ-IgGs of the patients vaccinated with Sputnik V (group 2) and the donors vaccinated after COVID-19 (group 3)." (PMID 37373231, 2023).
COVID-19 (continued). "The level of catalase activity of the IgG preparations of the patients who recovered from COVID-19 differed statistically (p < 0.05) from the activity of antibodies from the other three groups." (PMID 37373231, 2023). "We reported that the expression and enzyme activity of SOD and CAT were incremented in the PBMCs and plasma of COVID-19 patients." (PMID 36493512, 2023). "Among the first results in the field of antioxidant protection in COVID-19 were data on reduced erythrocyte activity of glutathione peroxidase, catalase, and superoxide dismutase in these patients compared to healthy individuals." (PMID 35361071, 2022). "CAT overexpression was accompanied by a significant increase in SOD mRNA levels in the placentae of the a-COVID-19 (p = 0.014, 2.12-fold increase) and s-COVID-19 (p = 0.041, 2.36-fold increase) groups compared to the CTRL group." (PMID 35327436, 2022). "Catalase activity decreased in the COVID-19 group, while an increase in 8-hydroxy-2’-deoxyguanosine, hydroperoxides, 15-FT-isoprostanes, and carbonyl groups were recorded in this group." (PMID 35204067, 2022). "In fact, patients from Serbia with moderate COVID-19 showed lower activity of the antioxidant enzyme catalase than individuals with severe disease, who also reported higher levels of superoxide anion radicals." (PMID 35746958, 2022). "We noted significantly higher CAT mRNA levels in the placenta of the a-COVID-19 (p = 0.006, 2.16-fold increase) and s-COVID-19 (p = 0.026, 2.19-fold increase) groups compared to the CTRL group." (PMID 35327436, 2022). "GGPPS1 is a catalase downstream of the mevalonate pathway, which is known for the synthesis of cholesterol and considered as a target to treat COVID-19." (PMID 35795000, 2022). "Recent studies have reported that catalase regulates cytokine in COVID-19, protects oxidative injuries, and inhibits replication of SARS-CoV-2." (PMID 34659433, 2021). "CAT placental levels were significantly different among groups (p < 0.05), with both COVID-19 groups showing a significant decrease in the post-hoc analysis, compared to controls (asymptomatic: p = 0.03; symptomatic: p = 0.02)." (PMID 34679654, 2021). "Seven core targets of vitamin A against COVID-19, including CAT, EGFR, ICAM1, IL10, MAPK1, MAPK14, and PRKCB, have been detected." (PMID 34335237, 2021). "Suppressed PEX3, PMP70 and PEX14 immunolabeling in vitro.Suppressed PEX3, PEX11β, PEX5L and PEX14 mRNA levels and decreased PMP70 and PEX14 protein levels in brain tissue from COVID-19 patients versus controls.Suppressed Pex3 mRNA and catalase protein in brains from infected hamsters." (PMID 40949164, 2025). "Furthermore, the authors observed an inverse correlation between catalase levels and inflammatory markers, implicating oxidative stress in the cytokine storm that is commonly seen in severe COVID-19 cases." (PMID 40332548, 2025). "Importantly, CAT enzymatic activity was significantly increased in the v-COVID-19 placentae relative to the u-COVID-19 placentae (p = 0.017, 1.1-fold increase)." (PMID 39768279, 2024). "Moreover, the v-COVID-19 placentae significantly over-expressed the CAT gene in comparison with the u-CTRL placentae (p = 0.007, 2.4-fold increase)." (PMID 39768279, 2024). "Importantly, a significant increase in placental CAT expression was reported in the v-COVID-19 relative to the u-COVID-19 subgroup (p = 0.034, 1.5-fold increase)." (PMID 39768279, 2024). "First, after the gel filtration of the COVID-19-IgGmix (equimolar mixture of 21 preparations) under conditions of the dissociation of noncovalent complexes in an acidic buffer (pH 2.6), the peak catalase activity of the IgGs precisely coincided with the peak (A280) of the IgG preparation absorption." (PMID 37373231, 2023).